PROSER3 (proline and serine rich 3)
Synonyms: C19orf55; FLJ30657
Tractability: No criterion of Open Targets' tractability assessment is met for any kind of drug.
Gene: Protein-coding gene on chromosome 19 (35,758,143 to 35,771,398, forward strand). Ensembl gene ENSG00000167595.
Subcellular location: Cytoplasm, cytoskeleton, microtubule organizing center, centrosome
Subcellular location (Human Protein Atlas): Golgi apparatus
Gene Ontology:
Molecular function: protein binding
Cellular component: centrosome
Genetic constraint (gnomAD): Loss-of-function variants: 33 observed, 47.15 expected, observed/expected ratio (o/e) 0.7, 90% interval 0.53 to 0.94. The upper end of that interval is the gene's LOEUF score, 0.94, which puts it in group 3 of 6, group 1 being the genes least tolerant of losing a copy. Missense variants: 623 observed, 588.62 expected, observed/expected ratio (o/e) 1.06, 90% interval 0.99 to 1.13. Synonymous variants: 266 observed, 245.68 expected, observed/expected ratio (o/e) 1.08, 90% interval 0.98 to 1.2.
Homologues: Orthologues: macaque PROSER3 (91% identical), chimpanzee PROSER3 (85% identical), pig PROSER3 (67% identical), rat Proser3 (53% identical), mouse Proser3 (52% identical), zebrafish proser3 (21% identical).
Diseases named in the same sentence as PROSER3 in open-access papers:
PROSER3 is named in the same sentence as 2 diseases in open-access papers, as found by Europe PMC text mining. Sharing a sentence is not in itself a finding about the gene and the disease. The quoted sentences say what the papers report.
cataract (1 paper, 2022). Partial or complete opacity of the crystalline lens of one or both eyes that decreases visual acuity and eventually results in blindness. "HMX1, GJA1, and PROSER3 were identified to be the leading genes associated with cataracts in our older population." (PMID 36009466, 2022). "Additionally, there were seven SNPs intersecting the groups containing all the cataract cases and those aged above 60; three of which (rs76840465, rs28433905, and rs60128322) could be mapped to the AGMO, SCFD2, and PROSER3 genes." (PMID 36009466, 2022).
prostate carcinoma (1 paper, 2024). A carcinoma that arises from epithelial cells of the prostate gland. "In contrast, PROSER3 did not affect the proliferation of prostate cancer cells." (PMID 38374143, 2024).